CTNNA2 (catenin alpha 2)
Description:
May function as a linker between cadherin adhesion receptors and the cytoskeleton to regulate cell-cell adhesion and differentiation in the nervous system (By similarity). Required for proper regulation of cortical neuronal migration and neurite growth. It acts as a negative regulator of Arp2/3 complex activity and Arp2/3-mediated actin polymerization. It thereby suppresses excessive actin branching which would impair neurite growth and stability. Regulates morphological plasticity of synapses and cerebellar and hippocampal lamination during development. Functions in the control of startle modulation (By similarity).
Synonyms: CAPR; CAP-R; CT114; CDCBM9; CTNR
Tractability: Antibody: UniProt places it where antibodies can reach, with medium confidence; its Gene Ontology location is reachable by antibodies, with medium confidence. PROTAC: ubiquitination databases record sites on it; its protein half-life has been measured.
Gene: Protein-coding gene on chromosome 2 (79,185,231 to 80,648,861, forward strand). Ensembl gene ENSG00000066032.
Subcellular location: Cell membrane; Cytoplasm; Cytoplasm, cytoskeleton; Cell junction, adherens junction; Cell projection, axon; Nucleus
Pathways (Reactome):
Developmental Biology: Myogenesis
Gene Ontology:
Molecular function: actin filament binding; cadherin binding; protein binding; beta-catenin binding; structural constituent of cytoskeleton; identical protein binding; structural molecule activity
Biological process: negative regulation of Arp2/3 complex-mediated actin nucleation; regulation of neuron migration; regulation of neuron projection development; axonogenesis; brain morphogenesis; cell migration; cell-cell adhesion; dendrite morphogenesis; prepulse inhibition; radial glia guided migration of Purkinje cell; regulation of synapse structural plasticity; cell adhesion; cytoskeleton organization; modification of postsynaptic actin cytoskeleton
Cellular component: cytoplasm; nucleus; adherens junction; axon; catenin complex; cytosol; plasma membrane; actin cytoskeleton; basolateral plasma membrane; cytoskeleton; extrinsic component of postsynaptic membrane; extrinsic component of presynaptic membrane; hippocampal mossy fiber to CA3 synapse; lamellipodium; parallel fiber to Purkinje cell synapse; postsynaptic density; postsynaptic density, intracellular component; presynaptic active zone cytoplasmic component
Genetic constraint (gnomAD): Loss-of-function variants: 33 observed, 89.9 expected, observed/expected ratio (o/e) 0.37, 90% interval 0.28 to 0.49. The upper end of that interval is the gene's LOEUF score, 0.49, which puts it in group 2 of 6, group 1 being the genes least tolerant of losing a copy. Missense variants: 787 observed, 1,126.6 expected, observed/expected ratio (o/e) 0.7, 90% interval 0.66 to 0.74. Synonymous variants: 414 observed, 432.47 expected, observed/expected ratio (o/e) 0.96, 90% interval 0.88 to 1.04.
Homologues: Orthologues: chimpanzee CTNNA2 (100% identical), guinea pig CTNNA2 (100% identical), macaque CTNNA2 (100% identical), dog CTNNA2 (99% identical), rabbit CTNNA2 (99% identical), rat Ctnna2 (99% identical), tropical clawed frog ctnna2 (96% identical), mouse Ctnna2 (95% identical), zebrafish ctnna2 (87% identical), Drosophila melanogaster alpha-Cat (61% identical), Caenorhabditis elegans hmp-1 (38% identical). Paralogues in human: CTNNA1 (78% identical), CTNNA3 (57% identical), VCL (21% identical), CTNNAL1 (19% identical).
Diseases named in the same sentence as CTNNA2 in open-access papers:
CTNNA2 is named in the same sentence as 58 diseases in open-access papers, as found by Europe PMC text mining. Sharing a sentence is not in itself a finding about the gene and the disease. The quoted sentences say what the papers report.
breast carcinoma (8 papers, 2016 to 2024). "Additional recurrently mutated genes detected in the 16 PALB2-associated breast cancers profiled by WES included CTNNA2, TMPRSS13, KRTAP4–11, LAMA5, KALRN, and COLL22A1 (all, n = 3)." (PMID 31428676, 2019). "Additionally, SNPs within CTNNA2 have recently been implicated in breast cancer and its role in tumor progression and metastasis has been suggested for multiple cancers." (PMID 27047539, 2016). "Another seven genes (CDH13, CDH7, CTNNA2, ERBB4, GRIK1, PCDH15, and TCF7L2) were reported as associated with the breast cancer by recent GWA studies." (PMID 28615668, 2017). "In addition to Rab5A, two proteins associated with cell motility, focal adhesion formation and cell-cell adhesion including ACTBL2 and CTNNA2 were also downregulated in breast cancer cells exposed to CB agonists." (PMID 39527598, 2024). "Four CpG sites located nearest the genes CTNNA2, GRB10, RPH3AL, and TINCR showed individual associations with breast cancer risk in a multivariable model (P < 0.05) and were also associated with breast cancer risk in matched case-control pairs in EPIC-Italy." (PMID 31039828, 2019). "Theα-catenin coding genes, CTNNA1, CTNNA2 and CTNNA3, participate carcinogenesis of multiple cancers, such as laryngeal carcinomas, oropharyngeal squamous cell carcinomas and breast cancer." (PMID 26882563, 2016).
schizophrenia (8 papers, 2012 to 2023). A major psychotic disorder characterized by abnormalities in the perception or expression of reality. "CTNNA2 encodes a neuronal-specific catenin protein that links cadherins to the cytoskeleton and is associated with bipolar disorder, schizophrenia, attention deficit hyperactivity disorder and excitement-seeking." (PMID 24995881, 2014). "The CTNNA2 gene encodes a catenin protein which is associated with several human psychiatric disorders with components of anxiety, including bipolar disorder and schizophrenia." (PMID 36890545, 2023). "Variants in CTNNA2 have also been implicated in schizophrenia and alcohol addiction." (PMID 27047539, 2016). "CTNNA2 (↑1.5 fold) is a schizophrenia susceptibility gene, and functions in dendrite morphogenesis, cell adhesion, and regulation of synaptic structural plasticity and has recently been implicated in a pluripotent stem cell model of schizophrenia." (PMID 24194745, 2013). "These miRNAs might therefore contribute to a differential regulation of CTNNA2 in humans, which could be linked to the dysregulation of gene expression associated with the emergence of schizophrenia." (PMID 22952683, 2012). "Although the human adult expression of CTNNA2 has been investigated only in schizophrenia, and pre-pulse inhibition is an endophenotype of schizophrenia, our results extend the relevance of CTNNA2 in a diverse set of psychiatric symptoms and also in a transdiagnostic endophenotype—rumination." (PMID 34577549, 2021). "Furthermore, CTNNA2 has also been shown to be involved in schizophrenia." (PMID 22952683, 2012). "The detected variants have not been previously studied; other CTNNA2 and PTPRD variants, however, have been linked to personality traits, such as impulsivity, schizophrenia, and autism, which manifest as unresponsiveness to visual stimuli." (PMID 38328521, 2023). "Moreover, many cis-NAT gene pairs in mammalian brain, including the genes involved in Alzheimer's disease and LRRTM1/Ctnna2, a pair of cis-NAT genes that participates in schizophrenia, can generate nat-siRNAs." (PMID 22439910, 2012).
laryngeal carcinoma (6 papers, 2016 to 2025). Carcinoma that arises from the laryngeal epithelium. "CTNNA2 is a tumor suppressor gene that is frequently mutated in some types of cancer, such as laryngeal carcinomas, and these mutations are associated with a worse prognosis." (PMID 40140215, 2025). "CTNNA2 is a tumor suppressor gene frequently mutated in laryngeal cancer, and CTNNA2 and CTNNA3 mutations increase the migration and invasion capabilities of head and neck squamous cell carcinoma cells." (PMID 34163353, 2021). "CTNNA2 has been shown to be frequently mutated in laryngeal carcinomas with mutations predictive of poor prognosis." (PMID 27047539, 2016). "In addition, the CTNNA2 mutation has been shown to be associated with the prognosis of gastric cancer, laryngeal cancer, and pancreatic ductal cancer." (PMID 34163353, 2021). "The decreased expression of CTNNA2 in tumors from our poor responders supports a pro-metastatic role for miR-223 as CTNNA2 acts as a tumor suppressor in both endometrial and laryngeal carcinomas." (PMID 33937369, 2021). "CTNNA2 and CTNNA3 are also frequently mutated tumor suppressor genes in laryngeal cancer." (PMID 34163353, 2021).
Alzheimer disease (4 papers, 2012 to 2025). A progressive, neurodegenerative disease characterized by loss of function and death of nerve cells in several areas of the brain leading to loss of cognitive function such as memory and language. "CTNNA2 has previously been associated with a number of phenotypes, including Alzheimer disease and blood pressure, whereas CDH18 has similarly been associated with blood pressure traits, including hypertension." (PMID 32889533, 2020). "CTNNA2 encodes for catenin (cadherin-associated protein), alpha 2 which functions as a linker between cadherin adhesion receptors and the cytoskeleton to regulate cell-cell adhesion, predominantly in the central nervous system, and it has been associated with late onset Alzheimer’s disease." (PMID 24725463, 2014).
Anxiety (3 papers, 2021 to 2025). Intense feelings of nervousness, tension, or panic often arise in response to interpersonal stresses. "One of the genes in the candidate region, CTNNA2 (Catenin alpha 2), has been thought to be involved in bipolar disorder, a disease with a component of anxiety." (PMID 36890545, 2023). "That said, together with findings in humans, these data contribute to the rationale for further study of CTNNA2 in anxiety-related behavior in animal models, and highlight a potential molecular mechanism that may drive stable anxiety across the lifespan." (PMID 34035480, 2021).
gastric cancer (3 papers, 2017 to 2021). A primary or metastatic malignant neoplasm involving the stomach. "According to reports, CTNNA2 mutation is involved in the adhesion junction pathway, which is one of the most disturbed pathways in gastric cancer." (PMID 34163353, 2021).
Obesity (3 papers, 2011 to 2025). Accumulation of substantial excess body fat. "In humans, variants located in KCNMA1 have consistently been associated with obesity, and CTNNA2 has been associated with plasma levels of vitamin K, that plays a crucial role in heart diseases and with cardiovascular measures of the autonomic tone." (PMID 32599723, 2020). "From this analysis, methylation data (β values) of cancer-related genes previously identified in the DNA of leukocytes from patients with obesity after following a VLCKD to lose weight were isolated (CCND1, MAPK10, GLI2, LAMC3 and CTNNA2)." (PMID 40140215, 2025).
alcohol addiction (2 papers, 2016 to 2018). "CTNNA2 has previously been identified as a risk gene for alcohol addiction." (PMID 29997484, 2018).
head and neck squamous cell carcinoma (2 papers, 2018 to 2021). A squamous cell carcinoma that arises from any of the following anatomic sites: lip and oral cavity, nasal cavity, paranasal sinuses, pharynx, larynx, and salivary glands. "CTNNA2 and CTNNA3 encode for cell-cell adhesions, and are thought to be tumor suppressors which are frequently mutated and implicated in head and neck squamous cell carcinoma." (PMID 30557297, 2018).
lung carcinoma (2 papers, 2015 to 2021). "However, the role of CTNNA2 mutation in lung cancer has not been studied, and the relationship between the tumor microenvironment and CTNNA2 mutation remains unknown." (PMID 34163353, 2021).
non-small cell lung carcinoma (2 papers, 2014 to 2021). A group of at least three distinct histological types of lung cancer, including non-small cell squamous cell carcinoma, adenocarcinoma, and large cell carcinoma. "Studies have shown that patients with advanced non-small-cell lung cancer who had more tumor antigens were more sensitive to immunotherapy, which suggests that LUAD patients with CTNNA2 mutation may be more likely to benefit from immunotherapy than those without this mutation." (PMID 34163353, 2021).
Parkinson's (2 papers, 2020 to 2025). "Among the first three predicted TFs that may bind and affect the transcription of CTNNA2, Foxo3 was reported to be neuroprotective in neurodegenerative diseases like Parkinson's and Huntington's disease." (PMID 40859434, 2025).
psychosis (2 papers, 2023 to 2024). "Moreover, DNA methylation difference in the CTNNA2 probe has also been reported in monozygotic twins discordant for psychosis." (PMID 38516266, 2024).
type 2 diabetes (2 papers, 2018 to 2020). "The host gene CTNNA2 was found among 24 novel candidate genes associated with type 2 diabetes risk in a African American subsample of 973 participants with type 2 diabetes and 104 healthy control participants in the GENNID study." (PMID 32894123, 2020).
acute myeloid leukemia (1 paper, 2017). Acute myeloid leukemia (AML) is a group of neoplasms arising from precursor cells committed to the myeloid cell-line differentiation. "While CTNNA2 has been found as hub for extracellular matrix organization, loss of CTNNA1 is exhibited by multiple cancer types, and restoration of CTNNA1 expression in acute myeloid leukemia cells led to lower proliferation." (PMID 29052507, 2017).
anaphylaxis (1 paper, 2019). An acute hypersensitivity reaction that occurs from exposure to an allergen. "This approach identified several genes that are associated with aging (ATP2B2, CAV3, CNTN3, CTNNA2, GRID2), inflammation (ATP2B2, CAV3, RAD18, KBTBD8), vascular permeability (SFXN5, RAD18) and anaphylaxis (CAV3, RAD18, CTNNA2, ATP2B2 and GRID2)." (PMID 31701027, 2019).
anxiety disorder (1 paper, 2021). A category of psychiatric disorders which are characterized by anxious feelings or fear often accompanied by physical symptoms associated with anxiety. "Interestingly, although not significantly enriched for average p value, the CTNNA2 gene was identified in the million veterans analysis of anxiety disorders, suggesting CTNNA2 is a relevant gene, like CRHR1, that is shared between human anxiety disorders and rhesus monkey infant-IT." (PMID 34035480, 2021).
depression (1 paper, 2021). "Our results suggest that CTNNA2 genetics may serve as biomarkers, and increasing the expression or function of CTNNA2 protein may be a potential new therapeutic approach in psychiatric disorders with perseverative negative thinking including, e.g., depression." (PMID 34577549, 2021).
epilepsy (1 paper, 2025). A brain disorder characterized by episodes of abnormally increased neuronal discharge resulting in transient episodes of sensory or motor neurological dysfunction, or psychic dysfunction. "In epilepsy, mapping our m6A-associated genes (e.g., PARP1, NBL1, RPL14) to their proteomic counterparts identified causal links to proteins such as ST6GALNAC5, CTNNA2, and TOM1L1, highlighting specific m6A-driven regulatory cascades at the protein level." (PMID 40624693, 2025).
esophageal cancer (1 paper, 2021). A primary or metastatic malignant neoplasm involving the esophagus. "Novel-miR-4885 can bind to the 3’ untranslated region of CTNNA2, thereby reducing cell adhesion and promoting the epithelial-mesenchymal transition of esophageal cancer cells." (PMID 34163353, 2021).
head and neck cancer (1 paper, 2016). A primary or metastatic malignant neoplasm affecting the head and neck. "CTNNA2 encodes α-catenin and was reported as a tumor repressor gene frequently mutated in head and neck cancers." (PMID 27409342, 2016).
human papillomavirus infection (1 paper, 2019). "Other groups have found that CTNNA2-promoter hypermethylation is associated with human papillomavirus infection in pharyngeal cancer." (PMID 31489113, 2019).
ischemia (1 paper, 2019). A hypoperfusion of the BLOOD through an organ or tissue caused by a PATHOLOGIC CONSTRICTION or obstruction of its BLOOD VESSELS, or an absence of BLOOD CIRCULATION. "In the present study, a significant decrease of the Ctnna2 expression was observed at 4 and 24 h of ischemia, suggesting that such fundamental processes become critical affected during the early phase of stroke." (PMID 31089963, 2019). "Four hours after ischemia onset, neocortical mRNA levels of all analyzed genes except VE-cadherin (Cdh5) were significantly down-regulated by about 50%, whereat the fold change ranged between 0.55 for α-catenin 2 (Ctnna2) and 0.38 for N-cadherin (Cdh2)." (PMID 31089963, 2019).
methamphetamine dependence (1 paper, 2021). A drug dependence that is a psychological dependency on the regular use of methamphetamine. "It is also noteworthy that CTNNA2, a DE gene in NIC SST and SA, is associated with not only SIn, but also alcohol, heroin, and methamphetamine dependence in Han Chinese." (PMID 34007041, 2021).
neuroblastoma (1 paper, 2019). Neuroblastoma (NB) is the most common solid, extracranial childhood tumor. "We correlated CTNNA2 (encodes α-N-catenin) expression to neuroblastoma disease relapse-free survival probability using publicly accessible human neuroblastoma datasets in R2 platform." (PMID 31489113, 2019). "Conversely, overexpressing CTNNA2 suppressed the neuroblastoma cell proliferation as measuring by the clonogenesis, inhibited anchorage-independent growth with soft agar colony formation assay." (PMID 31489113, 2019). "We analyzed the relationship between CTNNA1 and CTNNA2 expression and patient prognoses in large, independent cohorts featuring all stages of neuroblastoma." (PMID 31489113, 2019). "First, we analyzed the expression of CTNNA2 in Versteeg’s dataset which contains gene expression profiles from 24 neuroblastoma cell lines." (PMID 31489113, 2019). "Together, these results demonstrate that restoration of CTNNA2 expression is an advantageous strategy for in vivo neuroblastoma growth inhibition and tumor angiogenesis suppression in non-MYCN-amplified tumors, but less effective in MYCN-amplified tumors." (PMID 31489113, 2019). "Together, these data demonstrate that decreased levels of CTNNA2 are worse and associated with disease relapse and mortality in neuroblastoma patients, especially in those with neuroblastoma lacking MYCN-amplification." (PMID 31489113, 2019). "We found that CTNNA1 and CTNNA2 had higher expressions, while CTNNA3 had consistently lower expression in both Wolf and Seeger datasets from patients with neuroblastoma." (PMID 31489113, 2019). "However, the exact role of CTNNA2 in neuroblastoma remains unknown." (PMID 31489113, 2019). "Therefore, we deduced that CTNNA2 is a potential tumor suppressor in neuroblastomas that lacked MYCN expression." (PMID 31489113, 2019). "Therefore, restoring the expression of α-N-catenin can be a novel therapeutic approach for neuroblastoma patients who have the deletion of CTNNA2 and lack of MYCN amplification." (PMID 31489113, 2019). "There was no correlative expression shown between MYCN and CTNNA2 in neuroblastoma cell lines." (PMID 31489113, 2019). "Here, we identified one novel tumor suppressor, α-N-catenin (CTNNA2), a cell adhesion molecule, silenced in some non-MYCN amplified neuroblastomas, correlated to low event-free survival probability." (PMID 31489113, 2019).
neuronal migration disorder (1 paper, 2021). "This site is located in the second intron within CTNNA2 which codes for the catenin alpha-2 protein which plays an important role in neurodevelopment by acting as a regulator for actin branching, with mutations in this gene associated with a neuronal migration disorder." (PMID 34750344, 2021).
orthostatic hypotension (1 paper, 2021). Sudden fall of the blood pressure of at least 20/10 mm Hg when a person stands up. "CTNNA2 SNPs may act on cardiovascular phenotypes through brain mechanisms other than rumination, as it has been hypothesized in case of CTNNA2 involvement in orthostatic hypotension." (PMID 34577549, 2021).